KLF18 (KLF transcription factor 18)
Gene: Protein-coding gene on chromosome 1 (44,137,821 to 44,141,631, reverse strand). Ensembl gene ENSG00000283039.
Subcellular location: Nucleus
Gene Ontology:
Molecular function: DNA-binding transcription factor activity, RNA polymerase II-specific; RNA polymerase II cis-regulatory region sequence-specific DNA binding; DNA-binding transcription activator activity, RNA polymerase II-specific
Biological process: regulation of transcription by RNA polymerase II; positive regulation of transcription by RNA polymerase II
Cellular component: nucleus
Homologues: Orthologues: chimpanzee KLF18 (65% identical), rat Zfp352 (18% identical), rat Zfp353 (17% identical), mouse Zfp352 (16% identical), Caenorhabditis elegans klf-1 (8% identical), Drosophila melanogaster CG42741 (8% identical), zebrafish si:ch211-117k10.3 (8% identical), zebrafish klf2a (7% identical), tropical clawed frog klf2 (7% identical), zebrafish klf2b (7% identical), tropical clawed frog klf17 (7% identical), zebrafish klf5l (7% identical), and 11 more. Paralogues in human: KLF5 (8% identical), KLF12 (7% identical), KLF8 (7% identical), KLF15 (7% identical), KLF11 (7% identical), KLF2 (7% identical), KLF4 (7% identical), SP8 (7% identical), KLF17 (6% identical), KLF3 (6% identical), SP9 (6% identical), SP7 (6% identical), and 10 more.